IL13RA2 (interleukin 13 receptor subunit alpha 2)
Diseases named in the same sentence as IL13RA2 in open-access papers (continued):
Sharing a sentence is not in itself a finding about the gene and the disease.
tumor (continued). "However, some CAR-T cell therapies in clinical trials are targeting antigens that are expressed in both tumor and normal tissues (e.g. mesothelin, GD2, and IL13Rα2) and are demonstrating favorable responses without obvious adverse effects." (PMID 32228854, 2020). "Indeed, we demonstrate that pre-treatment of tumor cell lines in vitro with TSA enhanced their sensitivity to IL-13-PE and made IL-13Rα2-negative cell lines extremely sensitive to IL-13-PE." (PMID 21477288, 2011). "In mouse models of GBM, CAR T cells labeled with 89Zr-oxine showed that IL13Rα2-CAR T cells were labeled successfully without reduced efficacy from labeling and labeled CAR T cells were successful in assessing cytokine production and tumor cytotoxicity as well as in vivo antitumor activity." (PMID 36828374, 2023). "Although target antigens are expressed on both tumor and normal cells, not all kinds of CAR-T cell therapies exhibit observable on-target, off-tumor toxicities, such as targeting carcinoembryonic antigen (CEA), mesothelin (MSLN), and Interleukin 13 receptor, Alpha2 (IL13Rα2)." (PMID 31783889, 2019).
cancer (95 papers, 2008 to 2025). A tumor composed of atypical neoplastic, often pleomorphic cells that invade other tissues. "The prognostic significance of IL-13Rα2 expression in human cancers is associated with its involvement in various oncogenic pathways." (PMID 39598436, 2024). "There is also a need for ongoing research into the mechanisms underlying the roles of IL-13Rα2 and EphA2 in cancer progression, the development of resistance, and the interplay with the TME." (PMID 38612592, 2024). "After EGFRvIII, the major cancer antigen expressed in almost 60% of GBM patients is interleukin-13 receptor alpha chain variant 2 (IL13Rα2)." (PMID 37445721, 2023). "Cytotoxicity and cytokine secretion mediated by CAR T cell variants mirror the results shown with engineered cell lines, further establishing the ability of these CAR T cell variants to react to a wide array of cancer types and IL13Rα2 expression levels." (PMID 35939683, 2022). "Immunohistochemical expression of IL13Rα2 was highly associated with cancer-specific survival and relapse-free survival by univariate and multivariate analysis in 229 RCC patients." (PMID 33917914, 2021). "They found the overexpression of the IL-13Rα2 chain in cancer tissue was associated with poor prognosis after gastrectomy." (PMID 33450900, 2021). "Overexpression of IL-13Rα2 has been associated with various cancers and targeted as an anti-cancer therapeutic." (PMID 31974500, 2020). "In turn, the upregulation of IL-13Rα2 has been reported in colorectal and gastric cancers and linked with local advancement and metastasis as well as poor prognosis." (PMID 32512917, 2020). "Previous reports showed that the expression of IL13Rα2 in other types of cancers had been associated with the progression of cancer by promoting metastatic and invasive abilities of cancer cells." (PMID 30718742, 2019). "Upregulation of IL13Rα2 has been linked to chronic inflammation, which may underlie its frequent expression in these various cancer types." (PMID 36829563, 2023). "Indeed, IL13Rα2 is considered a cancer/testis antigen, which are usually associated to tumors of high histological grade and late clinical stages." (PMID 33917458, 2021). "Moreover, in cancer studies, IL-13Rα2 activation/signaling has been associated with TGF-β production in the absence of functional IL-4Rα." (PMID 34062727, 2021). "The low expression level of IL13Rα2 in RKO and CT-26 is rather surprising as IL13Rα2 overexpression is associated with more aggressive, mesenchymal cancer phenotypes and we have previously found a significant association between high IL13Rα2 expression and high grade and colloid tumors." (PMID 33917458, 2021). "Taken together, we investigated the clinicopathologically significant oncogenic role of IL13Rα2 in 229 RCC patients and the high expression of IL13Rα2 was significantly associated with cancer-specific survival and relapse-free survival in univariate and multivariate analysis." (PMID 33917914, 2021). "IL13Rα2 has been classified as a cancer/testis-like tumor antigen encoded in chromosome X." (PMID 32098194, 2020). "Drug resistance associated with cancer cells expressing IL13Rα2 may be due in part to the anti-apoptotic nature of this receptor." (PMID 29304038, 2018). "IL-13 receptor subunit alpha-2 (IL13Rα2) is associated with poor prognosis in some cancers." (PMID 26418721, 2015). "IL13Rα2 is also associated with poor prognosis in human cancers and a target for cancer therapy." (PMID 26418721, 2015). "Therefore, all the findings from the RNA-Seq data suggest that IL13Ra2 expression is associated with increased malignancy, such as high cell proliferation, cancer stem cell properties, and malicious genetic mutations (H3.3-K27M), which were also revealed in the TMA study." (PMID 38201655, 2024). "Interestingly, dysregulation of IL-13Rα2 has been associated with many cancers." (PMID 34062727, 2021).
cancer (continued). "This approach induced apoptosis in cancer cells, demonstrating the potential of receptor-specific peptides in mediating targeted cytotoxicity against malignancies expressing IL-13Rα2." (PMID 38612592, 2024). "Investigations into TNBC and Her-2-enriched cancer models have revealed a correlation between IL-13Rα2 expression, the occurrence of brain metastases, and diminished survival outcomes." (PMID 38612592, 2024). "The second study also demonstrated the dose-dependent effect of Dx in reducing the efficacy to eliminate cancer cells of IL13Rα2 CAR T cells." (PMID 38475830, 2024). "With the increase in malignancy grade expression of IL13Rα2 is a prognostic indicator for poor patient survival.In recent times personalized cancer therapy is emerging as a preferred therapy for cancer treatment." (PMID 38523646, 2024). "To develop novel anti‐cancer approaches, we constructed a chimeric antigen receptor construct using a high binding and codon optimised scFv‐IL‐13Rα2 fragment fused with CD3ζ and co‐stimulatory cytoplasmic domains of CD28 and 4‐1BB." (PMID 38685487, 2024). "Compared to luminal primary BCA cells, basal cancer cells exhibited significantly higher levels of the IL-13Rα2 decoy receptor." (PMID 38612592, 2024). "Interleukin 13 receptor subunit alpha 2 (IL13RA2) plays an essential role in the progression of many cancers." (PMID 39220137, 2024). "Our review highlights IL-13Rα2 and EphA2 as clinically relevant biomarkers for these cancer subtypes, noting their minimal expression in normal tissue, which underscores their potential as targets for CAR T-cell therapy." (PMID 38612592, 2024). "Background/Objectives: Interleukin 13 receptor alpha 2 (IL-13Rα2) is a receptor with a high affinity for IL-13 and is involved in the progression of human cancers." (PMID 39598436, 2024). "We have developed a novel hybrid lytic peptide (Pep-1-Phor21) to specifically target cancer cells overexpressing IL-13Rα2." (PMID 36830725, 2023). "While this work was in progress, two more anti-cancer peptides that target IL-13Rα2 were identified." (PMID 37345109, 2023). "Overall, the results support that the mechanisms of IL13Rα2-triggered cancer progression are relatively homogenous, with minor differences likely caused by the different genetic background (i.e. APC mutations in CRC)." (PMID 37963919, 2023). "A substantial increase in the expression of IL-13Rα2 was also detected in the more aggressive cancer cell lines (DU145 and PC-3) when they were grown as spheroids and treated with TSA or 5-aza-dC." (PMID 36830725, 2023). "In this study, we have demonstrated that Pep-1-Phor21 has therapeutic applicability by targeting cancer cells expressing IL-13Rα2." (PMID 36830725, 2023). "Further, when we down-regulated IL-13R α2 expression in the cancer cells via siRNA treatment, they lost sensitivity to Pep-1-Phor21, confirming that this hybrid peptide kills the cancer cells by targeting IL-13Rα2." (PMID 36830725, 2023). "LNCaP cancer cell spheroids, which normally have low levels of IL-13Rα2, showed increased expression levels of IL-13Rα2 mRNA, which was significant, with 10 μM of TSA treatment." (PMID 36830725, 2023). "In this study, our data were retrieved from cancer cell lines with different levels of IL13Rα2 expression and representing different cancer types." (PMID 37963919, 2023). "By inserting the gene for a special CAR receptor into the T cells, the CAR T cells (EGFRvIII-CAR, IL13Rα2-CAR, or HER2-CAR) can kill cancer cells by binding to the antigen, EGFRvIII, IL13Rα2, or HER2, that is overexpressed on GBM cells." (PMID 37445721, 2023). "Taken together, these results indicate an excellent prognostic value for SHN3 in multiple IL13Rα2-positive cancers." (PMID 37963919, 2023). "In this mini-review, we discuss recent developments surrounding IL-13Rα2-targeted therapies in pre-clinical and clinical study, including potential strategies to improve IL-13Rα2-directed cancer treatment efficacy." (PMID 35464460, 2022).
cancer (continued). "In conclusion, IL13-mutein CAR T cells show improved selectivity for IL13Rα2-expressing cancer cells relative to IL13Rα1-expressing tumors." (PMID 35939683, 2022). "This type of cancer exhibits the potential of metastasis and extravasations from breast to the lungs and is characterized by overexpression of IL13Rα2 genes." (PMID 35612318, 2022). "YKL-40 can bind chitin, heparin, collagen, and hyaluronan, and it has been suggested to promote cancer through binding to the IL-13Rα2, RAGE, syndecan-1, and CD44v3 receptors on the surface of cancer cells." (PMID 35631632, 2022). "IL‐13Rα2 overexpression induced by treatment with IL‐13 increased the expression of genes responsible for cancer growth and migration such as ERK, AP‐1, and MMP." (PMID 34758182, 2022). "Despite differences in affinity for IL13Rα2, all of the IL13-variant CARs demonstrated effector activity when exposed to IL13Rα2-expressing cancer cells and recombinant IL13Rα2 antigen." (PMID 35939683, 2022). "IL-13Rα2 is a high-affinity binding protein for its ligand IL-13 and a cancer-testis antigen as it is expressed in the testis." (PMID 34201539, 2021). "IL-13Rα2 is also expressed in diseased cells such as fibroblasts that are involved in various inflammatory diseases, including cancer." (PMID 34201539, 2021). "The high expression of IL13Rα2 was closely related to relapse-free survival in specific cancers in univariate and multivariate analysis." (PMID 33917914, 2021). "The expression of IL-13Rα2 in cancer tissues is commonly evaluated by quantitative or semi-quantitative immunohistochemistry (IHC), and less commonly by in situ hybridization (ISH)." (PMID 34201539, 2021). "Initially considered a decoy receptor, we and others have demonstrated beyond reasonable doubt that IL13Rα2 is also a functional receptor for IL-13 signaling transmission in cancer cells." (PMID 33917458, 2021). "IL13Rα2 has been repeatedly reported as an excellent therapeutic target for multiple types of advanced cancers." (PMID 33917458, 2021). "Recently, IL13Rα2 has been considered an important target for cancer treatment in various clinical studies." (PMID 33917914, 2021). "Studies have shown that IL-13-Pseudomonas exotoxin (IL-13-PE38QQR) is highly cytotoxic in vitro and in vivo to several types of IL-13Rα2-positive cancer cells including ACC cells." (PMID 33591997, 2021). "Over-expression of interleukin-13 receptor α2 (IL13Rα2) is observed in several cancer diseases such as glioma, colorectal and pancreatic cancer." (PMID 34206792, 2021). "Although IL-13Rα1 is expressed at basal levels and uniformly in a variety of cancer and non-cancer cells and tissues, IL-13Rα2 is predominantly overexpressed in a variety of solid cancers and inflammatory pathologies." (PMID 34201539, 2021). "Here, we investigated the IL13Rα2 interactome searching for novel targets in cancer invasion and metastasis." (PMID 32098194, 2020). "Initially, the IL-13/IL-13Rα2 axis was demonstrated to mediate signaling through AP-1 transcriptional pathway in a number of human cancers." (PMID 32098194, 2020). "In this report, we discovered the association between IL13Rα2 and the tyrosine phosphatase PTP1B for IL-13 signaling in different cancer types, paving the way to the therapeutic use of PTP1B inhibitors." (PMID 32098194, 2020). "The plausible extension to other IL13Rα2-expressing cancers increases the value of PTP1B inhibitors as potential therapeutic agents for cancer invasion and metastasis." (PMID 32098194, 2020). "In summary, PTP1B-silencing inhibited the Src/AKT/ERK pathway activation induced by IL-13 binding to IL13Rα2 in cancer cells." (PMID 32098194, 2020). "The number of PL and Ne positive PDAC were found to be significantly higher in the IL-13Rα2-positive cancers." (PMID 32443847, 2020). "The most significant effects of Claramine were observed in its capacity to inhibit cell migration and invasion in the three types of cancer, in a similar way to the IL13Rα2 antibody." (PMID 32098194, 2020).
cancer (continued). "We uncovered the relevance of PTP1B-mediated Src activation for IL-13 signaling through IL13Rα2 in multiple types of cancer." (PMID 32098194, 2020). "IL-13Rα2-positive cancers showed 36% (56/156) invasion of peripancreatic neuroplexus (PL), while IL-13Rα2-negative cancer showed only 16% (13/80) in the combined data from both hospitals." (PMID 32443847, 2020). "A better understanding of the IL13/IL13Rα2 signaling pathway would facilitate the discovery of novel therapeutic candidates in those cancers characterized by high expression of IL13Rα2, such as colorectal, ovarian, or GBM." (PMID 32098194, 2020). "In fact, by taking advantage of the high affinity of IL13Rα2 for IL-13 as well as its cancer cell-specific expression, several therapeutic agents targeting IL13Rα2 have been designed." (PMID 30718742, 2019). "In these models, IL-13 mediated cancer invasion and metastasis through IL-13Rα2 and signaling via AP-1/ERK pathway." (PMID 30572904, 2018). "Earlier studies have demonstrated that IL13Rα2 is a viable therapeutic target for malignant and invasive cancer therapy." (PMID 29304038, 2018). "We have also demonstrated that IL-13Rα2 can serve as a target for cancer immunotherapy in several pre-clinical and clinical studies." (PMID 30572904, 2018). "IL-13Rα2 is significantly upregulated in a number of human cancers and has been successfully applied as therapeutic target of chimeric antigen receptor (CAR)-engineered T cells in a patient with recurrent multifocal glioblastoma." (PMID 30165890, 2018). "Our previous studies on pancreatic ductal adenocarcinoma mouse model of human cancer suggested that IL-13 can mediate AP-1 signaling in IL-13Rα2 positive tumors." (PMID 30572904, 2018). "This work demonstrates that [64Cu]Pep-1L selectively binds hIL13RA2-expressing tumors and validates Pep-1L as an effective platform to deliver diagnostics and therapeutics to IL13RA2-expressing cancers." (PMID 28881623, 2017). "Upon re-analysis, IL-13Rα2 is identified to be enriched in MAPK signaling pathway (p = 4.31 × 10−4) and the pathway associated with cancer (p = 3.48 × 10−3)." (PMID 29203859, 2017). "In this context, these findings showed that CHI3L1 promoted cancer cell metastasis by interacting with IL-13Rα2 on cancer cell membranes." (PMID 28143526, 2017). "Confocal microscopy analysis demonstrated that CHI3L1 protein was co-localized with IL-13Rα2 on the plasma membrane of cancer cells." (PMID 28143526, 2017). "The results showed that knockdown of IL-13Rα2 gene expression in cancer cells significantly reduced the CHI3L1-induced activation of AP-1 transcription factors and upregulation of MMP gene expression in cancer cells." (PMID 28143526, 2017). "The CHI3L1 protein functioned by interacting with interleukin-13 receptor α2 chain (IL-13Rα2) molecules on the plasma membranes of cancer cells." (PMID 28143526, 2017). "These in vitro uptake data demonstrate binding and specificity of [64Cu]Pep-1L towards IL-13RA2-expressing cancer cells." (PMID 28881623, 2017). "An antibody against the interleukin-13 receptor subunit alpha-2 (IL13Rα2), an antigen found to be over-expressed in many cancer types was used as the model compound." (PMID 28915667, 2017). "As this and other types of therapies are implemented against IL13RA2 in peripheral cancers that widely express IL13RA2, it is critical to develop a molecular imaging technique to confirm uniform biomarker expression for patient stratification." (PMID 28881623, 2017). "IL-13Rα2, one of the IL-13 receptors, is highly expressed in some cancer cells, including GBM23 and OSCC24; therefore, targeting this receptor, such as CAR-T and IL13-PE, would be new strategy for these cancer patients." (PMID 27271009, 2016). "The generation of a targeting agent that strictly binds to IL13Rα2 will significantly expand the therapeutic potential for the treatment of IL13Rα2-expressing cancers." (PMID 26656559, 2015).